GZMB (granzyme B)
Diseases named in the same sentence as GZMB in open-access papers (continued):
Sharing a sentence is not in itself a finding about the gene and the disease.
infection (continued). "Hobit is required for NKT cells to upregulate granzyme B after stimulation with pro-inflammatory cytokines such as type I IFN and after infection with mCMV." (PMID 30131803, 2018). "On the other hand, IL-27 can enhance NK cell antitumor activity, including upregulation of Tbet and granzyme B in vivo, both of which we found to require IL-27 for optimal upregulation after LCMV Cl13 infection." (PMID 29593047, 2018). "Frequency of granzyme B+ correlates positively with lesion size; increased CD107a expression on CD8+ T cells upon infection." (PMID 29091132, 2017). "In contrast to naïve animals, N67C infection leads to increased levels of cleaved caspase-3, cleaved caspase-8, cleaved PARP, and granzyme B (GrzB) on days 4 and 6 p.i." (PMID 28874800, 2017). "With the aim of evaluating whether gzmA and/or gzmB deficiency influences local bacterial outgrowth and subsequent dissemination, we determined bacterial loads in the PLF, blood, and liver and lung homogenates of WT, gzmA−/−, gzmB−/−, and gzmAxB−/− mice at predefined time points after infection." (PMID 28694562, 2017). "In TLR2/9−/− mice TG large amount of granzyme B was produced by NK T, NK and CD8+ cells after infection." (PMID 28222752, 2017). "Accordingly, a recent study demonstrated that granzyme B- and perforin-producing CD4+ T cells were able to recognize and kill influenza virus-infected cells at the site of infection." (PMID 28289418, 2017). "We found similar expression of granzyme B and perforin in CD38+ and CD38- CD8+ T cells before infection." (PMID 27930660, 2016). "MAIT cells were readily and specifically activated in response to DENV-treated APCs (multiplicity of infection (MOI)=1), as indicated by production of IFN-γ and Granzyme B, as well as, expression of CD38, with minimal production of TNF-α." (PMID 27337592, 2016). "We found that the cytolytic proteins perforin and granzyme B were initially expressed in SIV-specific CD8+ T cells in tissues where viral replication and reservoir are established during the earliest phases of infection." (PMID 28036372, 2016). "Reduced granzyme B expression in the out-of-sequence CD8 T cells was seen as early as day 4 post infection and lasted at least until day 6 post infection." (PMID 25255454, 2014). "Poly(I∶C)-pretreated CD8 T cells degranulated, as shown by CD107a/b staining, but they had reduced granzyme B expression, suggesting that poly(I∶C)-pretreated CD8 T cells have lower cytolytic capabilities at day 5 post-infection." (PMID 25255454, 2014). "A similar trend was observed with proliferating and cytotoxic granzyme B + CD8 T cells which were lower in the lungs and lymph nodes of aged compared to their juvenile counterparts at most infection time points (unpaired student T-test)." (PMID 24642138, 2014). "Using intracellular cytokine staining (ICS) and granzyme B (GzmB) expression assays, data revealed that VV-specific effector CD8+ T cells emerged on day 5 post-infection (p.i.), peaked on day 7 p.i. and gradually declined from days 14–28 p.i. with VV-WR." (PMID 23383283, 2013). "Cytotoxic CD4+ T cell population appears at early stages of the infection concomitantly with high levels of IFN-γ and granzyme B expression." (PMID 24367519, 2013). "At 5 days post-infection, the CD8+ T cell population in the spleen expressed high levels of Granzyme B and was able to synthesize IFN-γ." (PMID 24367519, 2013). "The cytotoxic potential of SSIEFARL specific CD8 T cells in the isotype and anti-PDL-1 treated groups of mice was compared by determining the proportion of intra-cellular granzyme B and cell surface CD107a/b expressing CD8 T cells at day 6 post-infection." (PMID 22808056, 2012). "GzmB+ Tc cells induced apoptosis to the same extend on peptide-pulsed and Mo- or HE-ECTV infected MEFs (4–5 h post-infection) compared to mock-treated targets." (PMID 19838298, 2009).
infection (continued). "In the infected mice (day 7 post infection), upon restimulation with SIINFEKL peptide, the OT1GFP cells synthesize effector cytokines such as IFN-γ, TNF-α and expressed increased levels of granzyme-B indicating that they are poised for cytolysis." (PMID 19578440, 2009). "Blocking IFN-γ at day 3 post-infection did not significantly alter the frequencies of Tcf-1+ and GzmB+ populations." (PMID 40169810, 2025). "In addition, interleukin (IL)-2, granulocyte-monocyte colony stimulating factor (GM-CSF), granzyme B, IFN-γ, and IL-4 were specifically released in response to infection with MeVac-VLQSQRTD and MeVac-SGKALVLQSQRTD." (PMID 41050431, 2025). "OAV infection and enhanced intratumoral infiltration of GZMB+ CD8+ cytotoxic T lymphocytes were detected via immunohistochemistry (IHC) of E1A and immunofluorescence of GZMB and CD8." (PMID 41429778, 2025). "Indeed, there was a significantly higher frequency of tetramer-specific IL-18Rαlo CD8 T cells producing granzyme B and perforin, as compared to the IL-18Rαhi CD8+ cells at the site of infection." (PMID 41285788, 2025). "However, Trim29IEC-KO adult mice had significantly higher frequencies of intraepithelial IFN-γ-expressing CD4+ T cells and Granzyme B-expressing CD4+ T cells in small intestines than Trim29fl/fl mice after EMCV infection for 3 days." (PMID 39396665, 2025). "Further, CD8+ T cells in the lung and spleen of BC-colonized GF mice expressed significantly higher levels of CD69, IFN-γ and granzyme B compared with those from noncolonized GF mice following IAV PR8 infection at 8 dpi." (PMID 39388633, 2024). "We show that GzmA and GzmB are required to protect mice against oral, but not intravenous, infection with Salmonella enterica serovar Typhimurium, consistent with an intestine-specific role." (PMID 39137883, 2024). "During an acute infection, SARS-CoV-2-specific CD8+ T cells mainly display an effector memory phenotype, characterized by the lack of CD45RA and CCR7 expression and producing high amounts of effector molecules, such as granzyme B, perforin, and IFN-γ." (PMID 39460293, 2024). "Notably, at 12 days post-infection, we found a reduction of the frequency and number of CD8+ T cells activated (CD44+) producing granzyme B and perforin in the spleen of CKO mice compared to WT mice." (PMID 37908369, 2023). "A small increase in CD69+ NK cells was observed in the lungs only at 24 hours and 72 hours, but no increase of Perforin+ and Granzyme B+ cells was detected at both 24 and 72 hours post-infection (MFI in S2C and S2D)." (PMID 37486946, 2023). "We next looked at granzyme B and NKG2D expression in vaginal OVA-specific cells and observed that 20%–40% of these cells expressed granzyme B and 50%–65% expressed NKG2D on day 3 after infection." (PMID 36951943, 2023). "Surprisingly, upregulation of cytotoxic genes, and in particular GZMB in people with HIV, was reported, which could be the result of the host immune response that developed over longer-term infection (20–48 days, compared to 7 days in the present study)." (PMID 37111397, 2023). "Fewer hCD3 T cells stained positive for perforin and granzyme B, and very few hCD3 T cells stained positive for hCD103 in the mice that had not recovered from infection by 25 dpi." (PMID 35348437, 2022). "This antigen-specific antibody-mediated infection was selectively coupled to chemokine ligand 5 (CCL5), interleukin 1β (IL-1β), and C-X-C motif chemokine ligand 10 (CXCL10) secretion and a reduction in granzyme B (GrB) release." (PMID 35862953, 2022). "A low but significant increase in granzyme B (GrzB) release was measured 48 h after MOPV infection, whereas a nonsignificant increase of endoglin levels was observed at the same timepoint for both viruses." (PMID 35337059, 2022). "Importantly, lung gene transcript expression was consistent with the cellular phenotype and functional data, with T cell responses including TBET, IFNG, GZMB, and PRF1 upregulation throughout infection." (PMID 36146518, 2022).
infection (continued). "GzmB allows for CTL transmigration in postcapillary venules and homing to the site of infection." (PMID 35326588, 2022). "Approximately 4% of cells in lung tissue expressed granzyme B, and the frequency was relatively stable, regardless of age and infection." (PMID 34471088, 2021). "While fetal Vγ9Vδ2 T cells express granzyme A (GzmA) in the absence of infection, they do not express granzyme B (GzmB) or perforin, the main cytotoxic effector molecules that can efficiently kill infected cells." (PMID 34255746, 2021). "The impaired upregulation of GzmB that we observed in Ifnar1-/- NK cells also occurs during non-lethal infection with mouse cytomegalovirus." (PMID 34015056, 2021). "In the absence of perforin staining, we use granzyme B and FasL – two molecules with potential for upregulation in infection, in particular HIV infection to denote CD8 T cells with potential for cytotoxicity." (PMID 34177929, 2021). "PRF1, GZMB, and GNLY genes expressed at the fifth day of infection were upregulated." (PMID 34945761, 2021). "In mice, vaccine-induced TRM cells patrol the liver sinusoids, form aggregates around infected hepatocytes and, based on expression of molecules such as GzmB, IFN-γ and TNF-α, potentially exert infection control through direct lysis and/or cytokine-mediated mechanisms." (PMID 33202970, 2020). "For this purpose, human macrophages were infected with wild-type (WT) Lm or a strain lacking LLO (ΔLLO) at a multiplicity of infection of 10 in the presence or absence of GzmB or the unspecific protease, trypsin." (PMID 32151975, 2020). "However, 37 days after challenge infection, NK cells from BCG vaccinated volunteers produced significantly more granzyme B (Mann–Whitney U-test: p = 0.03) with a tendency towards increased degranulation, compared to controls." (PMID 30787276, 2019). "As for CD107a and perforin, there was a clear increase in the frequency of granzyme B (GrB) and IFN-γ producing NK cells on day 3 post-infection compared to uninfected controls, indicative for efficient in vivo priming, but no genotype-dependent differences were observed." (PMID 32038647, 2019). "Whatever the reason, GzmB is produced and released in the seabream brain upon NNV infection, suggesting a greater local CMC activity, which could be a key factor for NNV clearance observed in seabream." (PMID 31736981, 2019). "The increased frequency and gMFI of intracellular granzyme B from these CD8+ T cells that was observed after PbA-infection did not change after DOX treatment." (PMID 29438386, 2018). "Unlike γδ T cells, production of granzyme B by CD8+ αβ T cells was also reduced at 6 days post-infection." (PMID 30619302, 2018). "The γδ T cells able to produce granzyme B were not present before infection, but their numbers increased after infection." (PMID 30619302, 2018). "Taken together, our data provide strong evidence that the responses mediated by DCs, Mo/Mφ, NK and CD8+ T lymphocytes through IL-1β, iNOS and granzyme B production, respectively, together with the production of type I IFN early in the infection, are crucial to host defense against HSV-1." (PMID 28222752, 2017). "Though it is not clear if those responses are leishmania-specific, deficiency in caspases-1/11 did not affect either GzmB or IFN-γ production by CD8 or CD4 T cells and parasite numbers detected at 5 weeks post-infection remained unchanged." (PMID 28192528, 2017). "Splenic CD4+ T cell and CD8+ T cell activation was, however, largely unaltered, as determined by comparing the levels of granzyme B, KLRG-1, and Ki-67 expression in IFN-γR−/− mice to the levels in VAV-Cre+ IFN-γR2flox/flox mice and WT mice on day 7 of infection." (PMID 28874445, 2017). "We analysed IFN-γ, granzyme B, TNF-α and IL-10 levels in PBMC from individuals cured of CL (CCLm), or with a probable asymptomatic L. major (HHRLm) or L. infantum (HHRLi) infection as well as in naïve control subjects (HLR), following stimulation with rLmlRAB or rLmlRABC." (PMID 28416006, 2017).
infection (continued). "More recently, high levels of granzyme B as well as activated CD8+ T cells were observed in response to SLA in healed VL or PKDL individuals, indicating a possible role of CD8+ T cells in resistance to infection, via the perforin-granzyme B pathway." (PMID 28416006, 2017). "Furthermore, the frequency of GzmB+ CD4 cells correlated inversely with RNA load during acute HFRS, suggesting a potential impact of CD4 CTL responses in the control of infection." (PMID 28167943, 2017). "Consistent with the straight infection data, GzmB expression was unaltered in the absence of dicer, suggesting that miRNAs are dispensable for regulating effector differentiation during post-activation stages of CD8 T cell responses." (PMID 27627450, 2016). "However, post-infection, CD38+ CD8+ T cells had a greater expression of granzyme B and perforin compared to CD38- CD8+ T cells." (PMID 27930660, 2016). "Our results represent a rare instance of GzmB expression by non-CTL/natural killer cells in the context of infection with a human pathogen." (PMID 26191409, 2015). "No significant changes in mRNA levels of CCR5 and Granzyme B were detected in this early phase of infection." (PMID 26512987, 2015). "After infection with LmOVA, both WT and ACC2ΔT mice exhibited equivalent expansion of OVA-specific CD8+ T cells as well as efficient expression of effector molecules, such as IFN-γ, TNF-α, and granzyme B." (PMID 26367121, 2015). "In contrast, cVac infection of HBV transgenic mice triggered IFNγ (black bar) and Granzyme B (black bar) expression by a small but significant fraction of the transferred intrahepatic COR93-specific CD8+ T cells without significantly increasing their expansion in the liver (black bars)." (PMID 23853599, 2013). "To study the cellular immune responses generated during Brucella infection we examined CD4+ and CD8+ T cell activation at several time points post-infection by measuring the surface expression of CD25, CD44 and the intracellular synthesis of effector molecules such as Granzyme B and IFN-γ." (PMID 24367519, 2013). "A limitation of this infection route is that IFN-γ production by lung NK cells at 2 days was detectable in only 2–3% of the recoverable NK cells, consistent with a previous study, while only ∼10% of the lung NK cells show granzyme B expression." (PMID 23300570, 2012). "Supporting these arguments are the data presented here that apoptosis induced by gzmB+ Tc cells is not abolished by ECTV infection." (PMID 19838298, 2009). "Thus, ex vivo ECTV-immune Tc cells recognise MEF with similar efficiency after infection with either virulent or attenuated ECTV, and degranulation correlated with apoptosis induced by gzmB+ Tc cells on MEFs." (PMID 19838298, 2009). "Increased expression of GzmB in MAIT cells from IGRA-negative contacts, in the absence of an IFN-γ response, suggests that GzmB+ MAIT cells may serve an important role in targeting and responding to Mtb-infected cells during the early stages of infection." (PMID 40825006, 2025). "We noticed that infection significantly increased the abundance of resident (CD49a single positive) TCRαβ+ CD8+ T cells able to produce IFN-γ or granzyme B in response to PMA/ionomycin restimulation, while no statistical difference was observed on CD49a-negative or CD49a/CD103 double-positive cells." (PMID 40300021, 2025). "Likewise, infection with P. yoelii 17XNL demonstrated anti-neoplastic efficacy in the Lewis lung cancer mouse model by modulating the TME, characterized by significantly elevated levels of granzyme B and perforin and notably reduced PD-L1 expression." (PMID 40247360, 2025). "Thus, the reduced Th1 responses and expression of IFNG, TNF, GZMB, and PRF1 in CD4+ Trms may indicate the impaired anti-infection capacity in COPD airways." (PMID 40589761, 2025).
infection (continued). "Interestingly, comprehensive profiling of immune responses to eukaryotic viruses revealed that infection with the persistent MNV strain CR6 induces an increase in granzyme B+ CD8+ T cells in the colonic LP, whereas the non-persistent strains CW3 did not." (PMID 39464882, 2024). "In addition to infection-induced inflammation, it has been reported that the anti-tumoral advantage observed in mice that do not express GzmB is lost when additionally GzmA is absent, that is, in GzmA/B dKO mice." (PMID 39137883, 2024). "The production of antiviral cytokines such as IFN-γ, Granzyme B and MIP-1β in macaques after the boost is particularly important for viral control and could lead to protection during a primary infection by killing infected cells before the setup of a viral reservoir." (PMID 35335093, 2022). "In the presence of granulocytic MDSC as well as monocytic MDSC, the reduction of granzyme B, CD107a, and NKG2D in splenic NK cells by MDSC point to a reduced cytotoxic ability of NK cells, which explains the reduced potential to clear the virus in A.BY/SnJ mice during the course of infection." (PMID 34065891, 2021). "Infections in the presence of GzmB induced no caspase activation as compared with infection only." (PMID 32151975, 2020). "Upon antigen encounter TRM cells rapidly produce different effector molecules including cytotoxic factors like granzyme B (GzmB) or perforin, and inflammatory cytokines such as Interferon-γ (IFN-γ) and Tumor Necrosis Factor (TNF) as observed in different organs and upon various infection model." (PMID 33202970, 2020). "Granzyme B expression by CD8+ T cells was reduced in 4X infected mice compared with 1X infected mice but IFN-γ production was not significantly affected by the number of infections." (PMID 30846985, 2019). "While these data do not explain the inverse pattern of granzyme A/granzyme B and perforin in infection-primed NK cells they provide evidence for fundamental differences regarding the regulation of transcription and translation for these cytotoxic mediators in NK cells." (PMID 32038647, 2019). "Remarkably, independent of the genotype infection-priming of NK cells resulted in an overall decreased abundance of virtually all detectable prototypic NK cell proteins with the exception of granzyme A and granzyme B that were even found at higher abundances." (PMID 32038647, 2019). "It has been shown before that CD8+ T cells are required for the early production of cytokines at the site of infection, contribute to the clearance of rabies virus from the CNS by enhancing IFN-γ production and the CNS inflammatory response, and kill infected cells by the release of granzyme B." (PMID 29367251, 2018). "Additionally, retro-miR-150 infection of mir-150−/− CD8+ T cells reduced expression of anergy-related genes Cbl-b, Egr2, and p27 and increased the expression of activation-induced molecules granzyme B, cyclin B1, and Blimp1 following anti-CD3/CD28 stimulation." (PMID 28572627, 2017). "In particular, they examined the expression of granzyme B, perforin, and IFNγ in CD4+ T cells from the lung and in draining mediastinal lymph nodes, showing the presence of cytolytic effector cells only at the site of infection, as further confirmed by the upregulation of CD107a in the same cells." (PMID 28289418, 2017). "Indeed, while SIV-specific CD8+ T cell responses expressing T-bet initially maintained granzyme B expression following degranulation in responses from SLT and blood, later in infection T-bet expression became de-coupled from granzyme B re-expression in stimulated SIV-specific CD8+ T cells." (PMID 28036372, 2016). "The kinetics of granzyme B-producing CD8+ T cells complemented the characteristic of the IFN-γ kinetics with increased numbers and MFI of granzyme B+ cells in CD4-Cre A20fl/fl mice in primary infection at day 7 p.i. but reduced numbers and MFI in reinfected mice at day 53 p.i.." (PMID 28004776, 2016).